CTLA4 (cytotoxic T-lymphocyte associated protein 4)
Diseases named in the same sentence as CTLA4 in open-access papers (continued):
Sharing a sentence is not in itself a finding about the gene and the disease.
tumor (continued). "In this regard, a combination of low-dose SNAP and anti-CTLA4 antibodies may induce a syngeneic effect on tumor regression." (PMID 36639681, 2023). "Particularly, non-specific CTLA4 inhibition (i.p.)was found to result in interstitial pneumonia of higher severity despite shorter observation period, implying that CTLA4 inhibition systemically or in non-tumor environments is detrimental as it yields more off target effects." (PMID 37259163, 2023). "Mainly, CD38 is co-expressed with PD-1 and CTLA-4 on tumor-infiltrating CD8+ TRM cells, identifying CD38 as a potential immune checkpoint marker that could be harnessed for HCC immunotherapy." (PMID 37377962, 2023). "Thus, we confirmed that DSP-0509 additively elevated tumor growth inhibition even in combination with anti-CTLA-4 antibody." (PMID 36793737, 2023). "Studies have shown that Tregs constitutively express CTLA-4 to exert its immunosuppressive, and Treg-specific CTLA-4 deficiency has been shown to interfere with immune self-tolerance and suppressive function of Treg in vivo and promote tumor immunity." (PMID 37426702, 2023). "Using preclinical models, it was shown that the blockade of CTLA-4 led to anti-tumour immunity." (PMID 39086690, 2023). "Simultaneous bsAB binding to the checkpoint regulators on the surface of T cells e.g., PD-L1 and CTLA-4, might potentiate anti-tumor immune response." (PMID 36900399, 2023). "Immune escape of tumor cells is mediated by the PD-1/PD-L1 axis and CTLA-4." (PMID 36647390, 2023). "Thus, conditionally active, tumor-selective anti-CTLA-4 antibodies would potentially display an improved therapeutic window." (PMID 37753969, 2023). "The mechanism of action for the combined treatment of anti-CTLA-4 antibody and metformin in tumors involves the alleviation of T-cell inhibition, enhancement of T-cell antitumor immune activity, and regulation of tumor cell metabolism, achieving a synergistic antitumor effect." (PMID 37860188, 2023). "The anti-tumor effects of CTLA-4 blockade have been shown to be accompanied by an increase in effector T cells and a decrease in Tregs, thereby leading to an elevated ratio of intratumoral effector T cells to Tregs in mouse tumor models." (PMID 37614504, 2023). "In both tumor models, dual IL-6 and CTLA-4 blockade significantly inhibited tumor growth." (PMID 36881480, 2023). "The expression of PD-L1 on tumor cells contributes to the prediction of clinical efficacy of ICI in some tumor types, such as non-small cell lung cancer, which take advantage of the crucial roles played by the PD-L1/PD-1 and CTLA4/CD80/CD86 axes in the evasion of immune surveillance." (PMID 37893096, 2023). "However, this study noted decreased anti-tumor immunological microenvironments and decreased CTLA4 and PDCD1 expression in NSCLC patients with Nrf2-activating MU." (PMID 37794491, 2023). "However, there has been an increased expression of inhibitory immune checkpoint, such as CTLA-4, on the surface of T cells which suppresses the immunological attack against tumor cells." (PMID 36923659, 2023). "Recently, numerous immune treatment methods, such as immune checkpoint blockade of co-inhibitory receptors using anti-PD1/PDL1 and anti-CTLA4, dendritic cell vaccines, and cytokine therapy, have been designed and therapeutically used to address tumor cell immune evasion." (PMID 36109471, 2023). "To further understand the efficacy of this combination, we tested whether dual blockade of Ly6C/PD-1 or Ly6C/CTLA-4 could produce the same complete tumor regression as triple blockade." (PMID 37449205, 2023). "In 1996, it was discovered that the anti-CTLA-4 antibody (Ab) demonstrated potent antitumor effects with its administration in tumor-transplanted mice, leading to the rejection of the tumor, even when anti-CTLA4 was given a week after initial transplantation of the tumor." (PMID 37259381, 2023). "Additionally, infiltrating effector Treg cells within tumor tissue highly express CTLA-4 compared to naïve Treg cells." (PMID 37055849, 2023).
tumor (continued). "Inhibition of neutrophils or PAD4-dependent NETosis senses tumor cells to PD-1/CTLA-4 therapy." (PMID 37936694, 2023). "Mice receiving combined IL-6 and CTLA-4 blockade experienced consistent tumor regression by BLI." (PMID 36881480, 2023). "Because PD1 and CTLA4 are commonly expressed on the surface of activated T cells, PD-1 monoclonal antibody and CTLA-4 monoclonal antibody could block inhibitory signaling from tumor cells." (PMID 36845098, 2023). "The efficacy of CTLA‐4 blockade is due to the tumor‐infiltrating Treg cell depletion or reduction." (PMID 37829505, 2023). "Interestingly, the syngeneic murine tumor model shown substantial sensitivity to anti-CTLA-4 immunotherapy, wherein our plant-produced anti-CTLA-4 was as sensitive as the commercial anti-CTLA-4 in suppressing growth of tumors positive for PD-L1 expression." (PMID 37711295, 2023). "CTLA-4 might suppress T-cell-mediated antitumor immune responses by attenuating tumor-specific T-cell activation before these T-cells eradicate the tumor." (PMID 37662962, 2023). "In another in vivo study of a BC mouse model, treatment with anti-CTLA-4 antibody delayed tumor growth, and anti-CTLA-4 antibody plus matrix metalloproteinase inhibitor therapy reduced the percentage of Tregs, Th17 cells, and MDSCs in tumors compared with the control group." (PMID 36816749, 2023). "The immune memory protected mice from cancer recurrence, as demonstrated by the ability of anti-CTLA4 therapy in conjunction with PLGA–ICG–R837–based photothermal treatment to protect treated mice from tumor cells rechallenged 40 days after first tumor ablation." (PMID 37089933, 2023). "We aimed to suppress the immunosuppressive signaling from the checkpoint CTLA-4/B7 axis using LPS-Nb36 and induce more efficient tumor-specific CTLs using the comprehensive DC-tumor fusion vaccine technology, thereby achieving superior antitumor functions of adoptive immunotherapy." (PMID 37419930, 2023). "They all have their own ligand on APC (such as CD80, CD86 for CTLA-4 or PD-L1 and PD-L2 for PD-1), and tumor cells, depending on tumor types, may substitute them, thus using this immune checkpoint machinery to avoid cell killing." (PMID 37370768, 2023). "In addition, the mice that received PD-1 and the immune checkpoint inhibitory receptor CTLA-4 antibody had notably increased tumor-free survival." (PMID 37895145, 2023). "For example, the tumor had a higher proportion of activated T cells and Tregs expressing CTLA-4." (PMID 37444407, 2023). "At present, five main types of tumor immunotherapy are known: 1) molecular targeted therapy; 2) immune checkpoint inhibitors (PD-1/L1 and CTLA-4 inhibitors); 3) adoptive cellular immunotherapy (CAR-T cellular immunotherapy, TCR-T cellular immunotherapy, etc.); 4) cytokine therapy; 5) tumor vaccines." (PMID 37554324, 2023). "By contrast, the percentage of R1 tumor-derived monocytes was higher in combo treated as compared to IgG treated controls or matched spleens, while the infiltrating monocytes from anti-PD-1/CTLA-4 treated tumors had decreased levels of R2 and R3 monocytes." (PMID 37449205, 2023). "Therefore, it was theorized that inhibiting CTLA-4 activity would have a positive effect on limiting tumor growth and immunosuppression." (PMID 37174089, 2023). "ICIs are a class of specific IgG antibodies that recognize the inhibitory immune checkpoints CTLA-4 or PD-1 and immune checkpoint ligand PD-L1/2, which restore or enhance the killing power of T cells against tumor cells by blocking the interaction with their ligands to achieve antitumor effects." (PMID 37240574, 2023). "When combined with immune checkpoint inhibitors such as anti-PD-1/PD-L1 and anti-CTLA-4 mAbs, curcumin presented excellent antitumor effects by downregulating cytokine secretion, inhibiting NF-κB pathway and promoting the infiltration of anti-tumor T cells." (PMID 37576404, 2023).
tumor (continued). "Moreover, CTLA-4 is a co-inhibitory protein usually seen on tumor cells that plays a vital role in immune checkpoint therapy by downregulating the activation and expansion of tumor reactive T cells." (PMID 37875976, 2023). "In addition, CSF-1 induces MDSC tumor invasion and combines the treatment of anti-CTLA-4 with CSF-1/CSF-1R to inhibit MDSC signaling." (PMID 37892995, 2023). "We assessed tumor immune microenvironment through the CIBERSORT algorithm, which demonstrated the upregulation of M1 Macrophages and activated DCs and high expression of key immune checkpoint molecules (CTLA4, PDCD1LG2, and HAVCR2) in high-risk group." (PMID 37730669, 2023). "Furthermore, the CD39 encoding gene ENTPD1 is among the most highly upregulated genes in CD8+ T cells isolated from tumor tissue, along with other T cell exhaustion marker encoding genes (HAVCR2, CTLA4, TIGIT)." (PMID 37648263, 2023). "Tumor cells suppress anti-tumor response of immune cells through high-expressed CTLA-4." (PMID 38025711, 2023). "Interestingly, we also observed a broader expression of CTLA4 in malignant NK cells and tumor‐infiltrating T cells." (PMID 37949673, 2023). "Indeed, introducing anti-CTLA-4 antibodies resulted in restoring CD8+ T cell tumor infiltration and motility." (PMID 38313431, 2023). "New immune-therapies are aimed at stimulating anti-tumor T-cell responses either through blockade of checkpoint inhibitors such as PD-1 and CTLA-4 or through the use of T cells with chimeric Ag receptors (CAR-T) that can respond to native Ag on tumor cells without MHC-mediated Ag presentation." (PMID 37087494, 2023). "It was hypothesized that tumor samples from these individuals would have a positive immune response to PD-1/PD-L1 or CTLA4 inhibitors, or both." (PMID 37033259, 2023). "Additionally, they revealed that the mRNA expression profiles of these cells are associated with better progression-free survival in anti-PD-1-treated patients and a reduction in the tumor size in anti-PD-1/CTLA-4-treated patients." (PMID 37176128, 2023). "Only the expression of TIGIT and CTLA-4 increased in both subsets at the tumor site." (PMID 37898752, 2023). "In keeping with these findings, the EOAI3402143 treatment alone or combination with anti-CTLA-4 significantly reduced the PD-1 protein abundance in tumor-infiltrating CD3+ T cells and enhanced the production of IFN-γ, TNF, and GzmB in tumor-infiltrating CD8+ T cells compared with control treatment." (PMID 37208329, 2023). "In addition, blocking CTLA-4 (using ipilimumab) led to an increased infiltration of CD8+ T cells into the tumor core." (PMID 37046685, 2023). "Based on these findings, the tumors with downregulated CTLA-4 may have enhanced anti-tumor immunity, better prognosis, and greater response to immunotherapy." (PMID 37197667, 2023). "In recent years, immunotherapy, mainly represented by immune checkpoint inhibitors, including PD-1/PD-L1 and CTLA-4 inhibitors, has been widely applied in the treatment of various cancers with satisfactory results, which has become an indelible milestone in tumor immunotherapy." (PMID 36726381, 2023). "However, only few data are available concerning the regulation and function of CTLA-4 protein expression in tumor cells to date." (PMID 37415208, 2023). "It has recently been shown in preclinical murine melanoma and breast cancer models that a PEG-b-poly(L-alanine) hydrogel permitted encapsulation and release of tumor lysate cells with granulocyte–macrophage colony stimulating factor (GMCSF), anti-PD-1, and anti-CTLA-4 simultaneously in the tumor." (PMID 36768997, 2023). "This was in line with the previous findings that CTLA4 could deeply affect the landscape of tumor‐infiltrating lymphocytes with an immunosuppressed phenotype." (PMID 36397666, 2023). "ICs were upregulated on stromal immune cells within the tumour including PD-L2, CTLA-4 and TIGIT." (PMID 36445478, 2023).
tumor (continued). "Within the TME, unregulated overexpression of CTLA-4 by the malignant T-cells can effectively arrest the T-cell immune response, interfere with the priming capacity of APCs, and accordingly lead to uncontrolled tumor growth." (PMID 37174089, 2023). "Thus, the maintenance of the lymphocyte count is more important in inducing anti-tumor effects in CTLA-4-based ICI, compared to the increased direct effect of PD-L1 (w1)." (PMID 37174706, 2023). "Additionally, Tregs express the immune checkpoint receptor cytotoxic T lymphocyte-associated antigen-4 (CTLA-4), which contributes to tumor immune tolerance." (PMID 38187388, 2023). "After FMT, researchers found that the microbiota could affect the IL‐12‐dependent Th1 immune response and promote tumor control in mice and patients during CTLA‐4 checkpoint‐blocking treatment, and protect intestinal function." (PMID 36807772, 2023). "Hence, targeting CTLA-4 is an attractive strategy for increasing immune efficacy against malignancies and improving the prognosis of tumor patients." (PMID 37568193, 2023). "DSP-0509 also showed enhanced anti-tumor activity in combination with anti-CTLA-4 antibody." (PMID 36793737, 2023). "PD-1 and CTLA-4 on effector T lymphocytes play essential functions in tumor immune response." (PMID 37894446, 2023). "Immunostaining for CTLA-4 was seen in cytoplasm of tumor cells." (PMID 36879122, 2023). "However, when examining the expression of CTLA-4 in T cells of the tumor microenvironment, we observed a higher percentage of CTLA-4 positive T cells in patients with a high Ann Arbor stage at presentation." (PMID 37305822, 2023). "Following the strategy established through IS-panel-10, the combination of STING-LNP and the CTLA4 antibody in the 4T1 tumor model resulted in significant tumor suppression, despite the cancer being resistant to immunotherapy, including immune checkpoint inhibitors." (PMID 37376208, 2023). "Since anti-CTLA-4 could restrict tumor-induced neutrophil accumulation, an anti-PD-1 + anti-CTLA-4 combination overcomes anti-PD-1 resistance in hosts with MSI-H tumors displaying abnormal neutrophil infiltration." (PMID 37492581, 2023). "In 1996, Allison and colleagues showed that antibodies directed against CTLA‐4 lead to rejection of existing tumours in a mouse model, and that this response remains in immunological memory on re‐challenge, suggesting a role for CTLA‐4 in tumour immune evasion." (PMID 36535890, 2023). "However, when the sequence was reversed, CD8+ T cells underwent massive apoptosis, and the anti-tumor effect of anti-CTLA-4 was weakened." (PMID 37920463, 2023). "The encouraging safety profile of tebotelimab may also facilitate immunotherapy opportunities in tumor types in which suboptimal exposures to anti-PD-1 or toxicity with CTLA-4 combinations have prevented clinical development." (PMID 37857711, 2023). "Based on preclinical data showing that radiotherapy could improve the tumor microenvironment and the antitumor effect of CTLA-4, these studies used radiotherapy as a boost for ipilimumab." (PMID 37546397, 2023). "IL-6 was reported recently to also inhibit anti-CTLA4 efficacy in mouse tumor models." (PMID 36599350, 2023). "Besides, CTLA-4 is constitutively expressed on CD4+ Tregs, later work demonstrated that the CTLA-4 antibody acted, at least partially, through Fcγ receptor (FcγR)-dependent depletion of tumor-infiltrating Treg cells." (PMID 37691932, 2023). "CTLA-4 is an inhibitory molecule present on T cells, and inhibiting it with immunotherapy can promote T cell activation and proliferation while also improving anti-tumor immunity." (PMID 36816749, 2023). "The combination of metformin with anti-CTLA-4 (clone 9D9) showed a substantial improvement in tumor shrinkage and cytotoxic T lymphocyte activity in 4T1 breast cancer, B16F10 melanoma, and CT26 colon cancer without significant body weight changes or observable damage in the kidneys or liver." (PMID 37460927, 2023).
tumor (continued). "CTLA4 has an important role in immune escape, as its expression on Tregs could suppress the anti-tumor immune response by inhibiting the proliferation of effector T lymphocytes and was associated with worse disease-free survival and overall-survival." (PMID 38017109, 2023). "Tumor-induced regulatory DC subset inhibit immunity via CTLA-4-dependent IL-10 and IDO production." (PMID 36845131, 2023). "Targeting ICOS and CTLA4 together was demonstrated to promote the anti-tumor effect, and the expression of ICOS could serve as a biomarker for predicting the efficacy of anti-CTLA4 therapy." (PMID 38127899, 2023). "The ferroptosis inducer ZVI-NP increases the anti-tumor effect by polarizing M2 macrophages to M1, decreasing the frequency of Treg, decreasing the expression of PD-L1 on tumor cells and PD-1/CTLA4 on CD8 + T cells, and increasing the anti-tumor immune response." (PMID 37598126, 2023). "Furthermore, our plant-produced anti-CTLA-4 antibody demonstrated comparable tumor volume reduction to those observed in the Yervoy® group at same dose (TGITV = 98.83%)." (PMID 37711295, 2023). "Combining CTLA-4 and PD-1 inhibitors could have a synergistic antitumor effect, resulting in enhanced activity and increased infiltration of tumor-infiltrating lymphocytes (TILs) as well as a decrease in regulatory T cells (Tregs) in the CCA microenvironment." (PMID 37376451, 2023). "Blocking of the two immune checkpoint proteins (PD-1/CTLA-4) may produces a synergistic effect on tumor." (PMID 37064113, 2023). "The tumor surroundings with excess lactate and fatty acids create a metabolic barrier for glycolytic effector cells and simultaneously promotes stability of regulatory T cells, which limits the effectiveness of anti-CTLA-4 checkpoint therapy." (PMID 38435479, 2023). "CAF-rich tumors exclude CD8+ T-cells at the tumor margin and upregulate the expression of CTLA-4." (PMID 36793444, 2023). "Second, we determined the synergy of ML323 with anti-CTLA4 in CT26 tumor-bearing mice." (PMID 37996458, 2023). "These inhibitors enhance the cytotoxicity of immune effector cells by affecting cytotoxic T-lymphocyte antigen-4 (CTLA4), programmed cell death protein 1 (PD-1), and PD-1 ligand (PD-L1), and improving the tumor microenvironment (TME) to resist tumor cell growth." (PMID 36308553, 2023). "Notably, PDL1 and CTLA4 Abs increased the proliferation of lymphocytes, tumor cell death and the synthesis of pro-inflammatory IFNγ at the expense of anti-inflammatory IL10 in triple-negative samples as well." (PMID 37686465, 2023). "Similarly, CTLA-4 was expressed on a significantly higher percentage of CD45+ cells in the tumour tissue compared with circulation." (PMID 36445478, 2023). "In addition, CTLA-4 displayed membranous and/or cytoplasmic positive staining on immune cells, especially in tumor infiltrating lymphocytes (TILs)." (PMID 37662962, 2023). "The team also verified that the composition of Bacteroides fragilis and/or Bacteroides thetaiotaomicron and Burkholderiales influenced interleukin 12 (IL‐12)–dependent T helper (TH1) immune responses, which contributed to tumor control of CTLA‐4 blockade in mice and patients." (PMID 35770869, 2023). "ICB therapy is an emerging immunotherapy aiming at blocking immunosuppressive tumor signals and restoring anti-tumor immune responses by targeting checkpoint receptors or ligands such as PD-1/PD-L1, CTLA-4, TIGIT, LAG-3, TIM3, among which PD-1/PD-L1 is the most common research object." (PMID 38283361, 2023). "Inhibition of CTLA-4 can make T cells proliferate and attack tumor cells." (PMID 37081982, 2023). "According to the current results, CTLA-4 expression on neoplastic cells may be essential for the pathogenesis of BC and the modulation of the tumor microenvironment, especially in triple-negative BC." (PMID 36901916, 2023).